GLI2 (GLI family zinc finger 2)
Diseases named in the same sentence as GLI2 in open-access papers (continued):
Sharing a sentence is not in itself a finding about the gene and the disease.
chondrosarcoma (3 papers, 2010 to 2023). A malignant cartilaginous matrix-producing mesenchymal neoplasm arising from the bone and soft tissue. "To elucidate potential underlying mechanisms, we identified GLI1 and GLI2 target genes in human chondrosarcoma." (PMID 30695055, 2019). "In this study we identified unique and overlapping GLI1 and GLI2 transcriptional targets in neoplastic chondrocytes taken from primary human chondrosarcoma which is known to exhibit activated Hh signaling." (PMID 30695055, 2019). "Identifying transcriptional targets of GLI1 and GLI2 in chondrosarcoma can provide mechanistic insight into the role of Hh signaling in tumor pathogenesis." (PMID 30695055, 2019). "Here we conducted ChIP-sequencing of GLI1and GLI2 targets in primary human chondrosarcoma cells and coupled this to expression data in order to identify Hh target genes in chondrosarcoma and elucidate potential mechanisms through which this pathway may be acting." (PMID 30695055, 2019). "We assessed the protein levels of GLI1 and GLI2 and found consistent results with the mRNA levels, suggesting that GANT-61 primarily reduces GLI1 expression rather than GLI2 in chondrosarcoma." (PMID 37488121, 2023).
ciliopathies (3 papers, 2016 to 2025). "In addition, Gli2 expression decreased significantly over time, but we did not detect evidence for ciliopathy." (PMID 32497091, 2020).
Cirrhosis (3 papers, 2013 to 2022). A chronic disorder of the liver in which liver tissue becomes scarred and is partially replaced by regenerative nodules and fibrotic tissue resulting in loss of liver function. "In summary, these data suggest a greater role of Shh/RhoA-signaling in the extrahepatic angiogenesis in cirrhosis, whereas Gli-2 is a predominant mediator of canonical Hh-pathway in non-cirrhotic portal hypertension." (PMID 26412302, 2015). "Interestingly, and similar to the findings in rats, in human cirrhosis the Hedgehog ligands, but not their effector Gli-2, are upregulated." (PMID 26412302, 2015).
colitis (3 papers, 2021 to 2025). Inflammation of the colon. "Besides, TNF-α/NF-κB/JMJD2D has a protective effect against DSS- or AOM/DSS-induced colitis via activation of Hh/Gli1/Gli2." (PMID 34702800, 2021).
congenital hypopituitarism (3 papers, 2020 to 2023). "The authors identified three novel pathogenic variants in GHRHR, OTX2, and GLI2 expanding the spectrum of variants associated with congenital hypopituitarism." (PMID 36288632, 2022). "To conclude, we describe 3 patients and an aborted fetus with biallelic variants in TBC1D32 ̧ a ciliary gene implicated in SHH signaling and leading to the correct localization of Gli2, a protein that is significantly implicated in the aetiology of congenital hypopituitarism and related disorders." (PMID 32060556, 2020).
gastric adenocarcinoma (3 papers, 2016 to 2021). "Subsequently, we detected GLI2 mRNA levels in 21 paired gastric adenocarcinoma and adjacent normal tissues from GC patients and found that GLI2 was highly expressed in 14/21 patients." (PMID 34657624, 2021). "Here we show that GLI2A, an activator form of the Hh pathway transcription factor GLI2, drives rapid development of gastric adenocarcinomas from Lgr5-expressing gastric stem cells." (PMID 26859571, 2016). "Our studies point to a stem cell origin for murine gastric adenocarcinomas and highlight the functional relevance of crosstalk between the Hh/Gli2 and mTOR pathways in cancer." (PMID 26859571, 2016).
liver cancer (3 papers, 2016 to 2020). An epithelial or non-epithelial malignant neoplasm that arises from the liver. "Furthermore, studies in liver cancer tissues demonstrated Gli2 gene ablation reduced the expression of c-myc and Bcl-2 and elevated the p27 expression which regulates the cell cycle, reduce proliferation and inhibits the growth of liver cancer cells." (PMID 32093152, 2020).
liver disease (3 papers, 2015 to 2017). "Next, we sought to identify potential Hh-responsive cells using GLI2, the marker used in all prior studies of Hh signaling within a liver disease context." (PMID 28187190, 2017).
lung squamous cell carcinoma (3 papers, 2014 to 2017). "With regard to GLI2, very little is characterized about its expression in NSCLC, and only correlation between nuclear GLI2 with sonic Hh expression in lung squamous cell carcinoma has been reported." (PMID 25103784, 2014). "Certain reports investigating NSCLC patients have described an overexpressed SHH-GLI2 axis associated with poorer progression-free survival as well as an overexpressed GLI-2 axis involved in cellular proliferation and apoptosis resistance in lung squamous cell carcinomas." (PMID 28978016, 2017).
microcephaly (3 papers, 2020 to 2025). A congenital or acquired developmental disorder in which the circumference of the head is smaller than normal for the person's age and sex. "In the human face, loss of Gli2 has been associated with several craniofacial anomalies presenting with loss-of-function Hh phenotypes such as microcephaly, hypotelorism and a single central incisor." (PMID 33006313, 2020). "Our data support the idea that microcephaly in humans caused by inactivating mutations in NDE1 might be due to abnormally long cilia and/or reduced Hedgehog activity (GLI2)." (PMID 34518642, 2021).
neuroblastoma (3 papers, 2014 to 2018). Neuroblastoma (NB) is the most common solid, extracranial childhood tumor. "GLI2, GLI3 and especially GLI1 knockdown reduced neuroblastoma cell growth compared with siRNA control." (PMID 25134527, 2014). "In neuroblastoma CSC-like the Gli factors act through cooperative functional interactions in target gene regulation although in our case it seems that GLI2 does not play an important role." (PMID 25392930, 2014). "GANT-61 is an inhibitor of GLI1 and GLI2, known to reduce autophagy in MYCN non-amplified, but not in MYCN amplified neuroblastoma (NB) cells." (PMID 29581853, 2018).
pancreatic ductal adenocarcinoma (3 papers, 2019 to 2024). An infiltrating adenocarcinoma that arises from the epithelial cells of the pancreas. "Subcutaneous injection of a murine pancreatic ductal adenocarcinoma cell line (KPC) with mouse Gli2/Gli3-knock-out (KO) fibroblasts in mice led to a reduction in tumor growth, decreased the recruitment of MDSCs and increased NK cells." (PMID 36674836, 2023). "In an invasive model of pancreatic ductal adenocarcinomas (PDA), the ablation of Gli2 and Gli3 in fibroblasts was shown to decrease tumor growth by recruiting NK cells during the late stages of tumorigenesis." (PMID 36674836, 2023).
psoriasis (3 papers, 2017 to 2023). An autoimmune condition characterized by red, well-delineated plaques with silvery scales that are usually on the extensor surfaces and scalp. "However, besides the incidental finding of some psoriasiform characteristics in a transgenic pig with constitutive cutaneous expression of the hedgehog transcriptional activator, Gli2, porcine models of psoriasis-like conditions have not, to our knowledge, been described." (PMID 28679670, 2017).
renal fibrosis (3 papers, 2018 to 2024). A final common manifestation of a wide variety of chronic kidney diseases characterized by glomerulosclerosis and tubulointerstitial fibrosis. "The pharmacological blockade and genetic ablation of GLI1 or GLI2 in these MSCs ameliorated renal fibrosis." (PMID 39766192, 2024). "Specifically, Gli2 drives cell cycle progression of myofibroblasts during renal fibrosis." (PMID 38177914, 2024). "In addition, researchers investigated the link between GLI1 and GLI2 mRNA expression and the extent of renal fibrosis in 10 human specimens, finding that increased GLI1 and GLI2 expression corresponded to a greater degree of fibrosis." (PMID 39766192, 2024).
systemic sclerosis (3 papers, 2020 to 2023). A chronic disorder, possibly autoimmune, marked by excessive production of collagen which results in hardening and thickening of body tissues. "Overexpression of HOTAIR in systemic sclerosis dermal fibroblasts induces the transcription factor GLI2, leading to the pro-fibrotic phenotype." (PMID 36869839, 2023). "HOTAIR induces GLI2 expression through Notch signaling in systemic sclerosis dermal fibroblasts." (PMID 35626352, 2022).
acute promyelocytic leukemia (2 papers, 2021 to 2022). An aggressive form of acute myeloid leukemia (AML), characterized by arrest of leukocyte differentiation at the promyelocyte stage, due to a specific chromosomal translocation t(15;17) in myeloid cells. "Interestingly, arsenic trioxide, which is an FDA-approved inhibitor of GLI1 and GLI2 transcription factors, is used as a single agent against acute promyelocytic leukemia." (PMID 35406554, 2022).
brain cancer (2 papers, 2013 to 2024). A primary or metastatic malignant neoplasm affecting the brain. "Suppression of GLI1/GLI2 reduced hTERT protein levels in human colon, prostate and brain cancer cells." (PMID 24086482, 2013). "Suppression of both GLI1 and GLI2 functions reduced hTERT mRNA and protein expression in human colon, prostate and brain cancer cell lines." (PMID 24086482, 2013).
celiac disease (2 papers, 2018 to 2021). An autoimmune genetic disorder with an unknown pattern of inheritance that primarily affects the digestive tract. "Wheat Gli-2 loci encode complex groups of α-gliadin prolamins that are important for breadmaking, but also major triggers of celiac disease (CD)." (PMID 29581476, 2018).
cerebellar tumor (2 papers, 2020 to 2023).
clear cell renal cell cancer (2 papers, 2014 to 2022). "A recent published study of clear cell renal cell cancer (ccRCC) raises another question that SPOP acts as multiple regulators of cellular proliferation and apoptosis, including not only Gli2 but also tumor suppressor - PTEN, ERK phosphatases and pro-apoptotic molecule Daxx." (PMID 25204354, 2014).
cleft lip (2 papers, 2019 to 2025). Congenital defect in the upper lip where the maxillary prominence fails to merge with the merged medial nasal prominences. "In parallel, a BOC nonsense variant (p.R681X), co‐segregating with a GLI2 missense variant (p.A543G), is identified in a multiplex family with microform cleft lip." (PMID 40464334, 2025). "In a sequence screening of NSCL/P patients, the variants p.Ser1555Pro and p.Ala268Val of GLI2 were found in patients presenting with primary features of cleft lip." (PMID 31386309, 2019). "Besides, our ES analysis of a multiplex family with microform cleft lip identified a monoallelic hypomorphic BOC nonsense variant, which was antagonized epistatically by a co‐transmitting monoallelic hypermorphic GLI2 missense variant in the carriers." (PMID 40464334, 2025). "Some variants of GLI2 have been detected in patients who present with cleft lip/palate by Sanger sequencing and are not in unrelated controls without orofacial cleft." (PMID 31386309, 2019).
cyst (2 papers, 2016 to 2025). A sac-like closed membranous structure that may be empty or contain fluid or amorphous material. "Large cyst-like structures are maintained in adult Gli2/3EKO skin and are also positive for squamous marker expression, e.g. filaggrin (Fig. EV3A–F)." (PMID 40859032, 2025). "Furthermore, Thm1 mutants with concomitant deletion of Gli2 have diminished cystogenesis, indicating that increased hedgehog signaling contributes towards cyst progression in that model." (PMID 27853247, 2016). "Interestingly, K10 and filaggrin, markers for supra-basal keratinocytes within the interfollicular epidermis, were both detected in the cyst-like abnormal HF structures in Gli2/3EKO mice, but not in HFs of littermate controls." (PMID 40859032, 2025).
graft versus host disease (2 papers, 2013 to 2020). An immune system disorder that occurs after allogeneic hematopoietic stem cell transplant and is a reaction of donor immune cells against host tissues. "We and others have shown that GLI1 and GLI2 are upregulated in SSc skin and fibroblasts and SHH pathway activation plays an important role in the pathogenesis of tissue fibrosis both in scleroderma and sclerotic graft versus host disease (GVHD)." (PMID 33303026, 2020).
Hypertension (2 papers, 2021 to 2022). The presence of chronic increased pressure in the systemic arterial system. "ULK4 and FHIT genes have 17 and 10 EH-associated SNPs, respectively, while FNDC3B, FHIT, NPPC-DIS3L2, GLI2, and RBM47 include SNPs that have a ≥4 log-p value association with hypertension in the studied cohort." (PMID 35629146, 2022). "In addition, we identified 21 common genes that are shared between the GWAS and text mining analyses; of these, FNDC3B, FHIT, NPPC-DIS3L2, GLI2, and RBM47 genes are the most highly associated with hypertension." (PMID 35629146, 2022).
hypoglycaemia (2 papers, 2020 to 2025). "In addition, hypoglycaemia, cholestasis, recurrent seizures and intellectual disability have been reported in patients with GLI2 mutations as a consequence of ACTH and GH deficiency." (PMID 31782289, 2020).
Intellectual disability (2 papers, 2020 to 2025). "Although intellectual disability is not a consistent feature of GLI2‐related conditions, neurodevelopmental challenges including speech and motor delays have been reported in several case series." (PMID 40908550, 2025).
keloid (2 papers, 2022 to 2023). An irregularly shaped, elevated mark on the skin caused by deposits of excessive amounts of collagen during wound healing. "The lncRNA AC073257.2 and its upstream target gene Gli2 were both upregulated in keloid." (PMID 36046343, 2022). "LncRNA AC073257.2 and HNF1A-AS1 might regulate keloid cell growth and proliferation by its target gene GLI2 and HNF1A respectively." (PMID 36046343, 2022).
microphthalmia (2 papers, 2007 to 2025). Congenital or developmental anomaly in which the eyeballs are abnormally small. "Loss of function in the GLI2 gene has been shown to cause microphthalmia and decreased head width in homozygous mice." (PMID 39754479, 2025). "Molecular analysis proved these eye defects to be independent of the gli2 mutation in the yot strain, and the yot genotype and phenotype were rapidly lost from carriers of this new variable eye trait, named AMN for anophthalmia, microphthalmia, and nanophthalmia." (PMID 17397257, 2007).
multiple myeloma (2 papers, 2019 to 2022). "Indeed, simultaneous inhibition of GLI with GANT58 and RSK2 with SL0101 has been reported to synergistically reduce GLI2 levels, enhancing apoptosis of multiple myeloma cells." (PMID 31244888, 2019). "Furthermore, the existence of non-canonical activation of HH signaling by the MEK1/RSK2 axis responsible for GLI2 stabilization in multiple myeloma strongly supports the development of novel therapeutic strategies targeting both pathways." (PMID 31244888, 2019). "The results showed that the expression levels of PTCH1, GLI2, Hes1, and SHH in RPMI 8226/R were greatly increased compared with the multiple myeloma drug-sensitive cell line RPMI 8226/S, while the expression level of GLI1 was notably decreased." (PMID 35813864, 2022). "In this study, the expression changes of PTCH1, GLI1, GLI2, Hes1, and SHH in the multiple myeloma drug-resistant cell line RPMI 8226/R were first detected." (PMID 35813864, 2022). "In multiple myelomas, the MEK1/RSK (ribosomal S6 kinase) cascade sustains non-canonical HH pathway activation through the stabilization of GLI2." (PMID 31244888, 2019).
oral squamous cell carcinoma (2 papers, 2016). "The authors reported that Gli-2 overexpression is associated with poorer outcomes in patients with oral squamous cell carcinoma undergoing surgery with or without radiotherapy." (PMID 27918595, 2016).
Osteopenia (2 papers, 2013 to 2022). Osteopenia is a term to define bone density that is not normal but also not as low as osteoporosis. "We report that expression of a constitutively active form of Gli2 (ΔNGli2) in the Osx-expressing cells and their progenies leads to osteopenia in postnatal growing mice, due to the suppression of osteoblast number and activity." (PMID 23383082, 2013).
osteoporosis (2 papers, 2023). A condition of reduced bone mass, with decreased cortical thickness and a decrease in the number and size of the trabeculae of cancellous bone (but normal chemical composition), resulting in increased fracture incidence. "We identified genes involved in pathogenesis of osteoporosis through Gene Expression Omnibus (GEO) database and subsequently selected Hedgehog signaling-related genes Shh, Ihh, Gli2, and Runx2 for assessment via qRT-PCR and ELISA, Western blotting." (PMID 38019761, 2023). "Additionally, bioinformatics analysis of the GEO dataset showed that Hedgehog signaling pathway was involved in pathogenesis of osteoporosis, especially related genes Shh, Ihh, Gli2, and Runx2." (PMID 38019761, 2023).
polydactyly (2 papers, 2025). A disease characterized by the presence of polydactyly, including syndromic and non-syndromic forms. "Most truncating GLI2 variants reported to date are associated with polydactyly." (PMID 41488893, 2025). "In a review of 112 individuals from 65 kindreds with GLI2 variants, only 37% of those with truncating variants had both pituitary anomalies and polydactyly, whereas non‐truncating variants were associated with a pituitary only phenotype in 92% of cases with incomplete penetrance." (PMID 40908550, 2025).
renal carcinoma (2 papers, 2020 to 2024). A carcinoma arising from the epithelium of the renal parenchyma or the renal pelvis. "For instance, in renal carcinoma cells, treatment with LDE225 showed reduced cell proliferation, concomitant with lower GLI1 and GLI2 expression." (PMID 33396427, 2020).
sarcoma (2 papers, 2011 to 2024). A usually aggressive malignant neoplasm of the soft tissue or bone. "In these sarcomas, it is likely that the Gli2 insertions lead to the expression of constitutive transcriptional activator forms of Gli2 that drive tumor formation." (PMID 22039523, 2011).
scleroderma (2 papers, 2021 to 2023). Scleroderma is a rare autoimmune connective tissue disorder characterized by abnormal hardening of the skin and, sometimes, other organs. "Hedgehog signaling and accumulation of Gli1 and Gli2 have been reported to have a role in scleroderma." (PMID 37700377, 2023). "The induction of the fibrotic phenotype of scleroderma is mediated through GLI1/GLI2 (the effector molecules of the Hedgehog pathway) to promote tissue fibrosis." (PMID 35008794, 2021). "GLI1/GLI2 (the effector molecules of the Hedgehog pathway) promote tissue fibrosis by inducing the fibrotic phenotype of scleroderma." (PMID 35008794, 2021).
serous ovarian cancer (2 papers, 2020 to 2025). "Representatively, the relative gene expression levels of HH pathway genes in 16 primary grade 3 serous ovarian cancer samples standardized against normal ovarian cell lines demonstrated higher GLI2 levels only in 25% of the samples." (PMID 40565349, 2025). "This analysis revealed an enrichment of SHH pathway genes, including GLI1, GLI2, HHIP, PTCH1, and PTCH2, in SSTs as compared to high-grade serous ovarian cancers and other sex cord-stromal tumors." (PMID 31896750, 2020).
spina bifida (2 papers, 2015 to 2026). A congenital neural tube defect in which vertebrae are not fully formed. "Furthermore, methylation and reduced expression of GLI2 in fetal brain have been associated with neural tube defect of the spina bifida." (PMID 41246799, 2026).
stenosis (2 papers, 2020 to 2021). "In addition, renal problems such as renal hypoplasia/dysplasia, urethral stricture and cardiac problems such as ASD/VSD have been reported in patients with GLI2 mutations." (PMID 31782289, 2020).